SLC12A1 (solute carrier family 12 member 1)
Description:
Renal sodium, potassium and chloride non-electrogenic ion symporter that mediates the transepithelial NaCl reabsorption in the thick ascending limb and plays an essential role in the urinary concentration and volume regulation. It can substitute NH4(+) for K(+), enabling NH4(+) apical transmembrane transport in the medullary thick ascending limb (MTAL). This function is crucial for maintaining ammonium homeostasis by the kidney, particularly during metabolic acidosis (By similarity).
Synonyms: BSC1; NKCC2; CCC2; BSC; BSC-1
Tractability: Small molecule: an approved drug acts on it; it belongs to a druggable protein family. Antibody: UniProt places it where antibodies can reach, with high confidence; its Gene Ontology location is reachable by antibodies, with high confidence; UniProt predicts a signal peptide or a membrane-spanning region.
Target class: Electrochemical transporter; SLC superfamily of solute carriers; Transporter; SLC12 family of cation-coupled chloride transporters
Gene: Protein-coding gene on chromosome 15 (48,178,438 to 48,304,078, forward strand). Ensembl gene ENSG00000074803.
Subcellular location: Apical cell membrane
Subcellular location (Human Protein Atlas): Vesicles; Nucleoplasm
Pathways (Reactome):
Disease: Defective SLC12A1 causes Bartter syndrome 1 (BS1)
Transport of small molecules: Cation-coupled Chloride cotransporters
Gene Ontology:
Molecular function: protein serine/threonine kinase binding; sodium:potassium:chloride symporter activity; sodium:ammonium:chloride symporter activity; chloride:monoatomic cation symporter activity; transmembrane transporter activity
Biological process: cell volume homeostasis; ammonium homeostasis; chloride transmembrane transport; chloride transport; monoatomic ion transmembrane transport; potassium ion transmembrane transport; sodium ion transmembrane transport; transepithelial ammonium transport; monoatomic ion transport; transmembrane transport
Cellular component: apical plasma membrane; extracellular exosome; membrane; plasma membrane
Genetic constraint (gnomAD): Loss-of-function variants: 64 observed, 81.16 expected, observed/expected ratio (o/e) 0.79, 90% interval 0.64 to 0.97. The upper end of that interval is the gene's LOEUF score, 0.97, which puts it in group 4 of 6, group 1 being the genes least tolerant of losing a copy. Missense variants: 933 observed, 965.79 expected, observed/expected ratio (o/e) 0.97, 90% interval 0.92 to 1.02. Synonymous variants: 361 observed, 345.02 expected, observed/expected ratio (o/e) 1.05, 90% interval 0.96 to 1.14.
Homologues: Orthologues: macaque SLC12A1 (99% identical), chimpanzee SLC12A1 (98% identical), dog SLC12A1 (96% identical), pig SLC12A1 (96% identical), rabbit SLC12A1 (94% identical), guinea pig SLC12A1 (93% identical), rat Slc12a1 (93% identical), mouse Slc12a1 (93% identical), tropical clawed frog slc12a1 (77% identical), Drosophila melanogaster Ncc69 (47% identical), zebrafish slc12a1 (44% identical), Caenorhabditis elegans nkcc-1 (43% identical), and 4 more. Paralogues in human: SLC12A2 (64% identical), SLC12A3 (48% identical), SLC12A6 (28% identical), SLC12A4 (27% identical), SLC12A5 (27% identical), SLC12A7 (26% identical), SLC12A9 (22% identical), SLC12A8 (17% identical).